LAG3 (lymphocyte activating 3)
Diseases named in the same sentence as LAG3 in open-access papers (continued):
Sharing a sentence is not in itself a finding about the gene and the disease.
tumor (continued). "Indeed, circulating tumor-specific T cells in metastatic melanoma patients are functional although those isolated from tumor-draining LNs exhibit exhausted characteristics (decreased IFN-γ and increased CTLA-4 and LAG-3 expression)." (PMID 28220121, 2017). "Moreover, CD3+CD4+ T cells and CD3+CD8+ T cells derived from 4T1-tumor bearing mice expressed higher level of immunosuppressive markers including PD1, PDL1, LAG3, CTLA4 and TIM3 in peripheral blood and spleen than that in normal mice." (PMID 29383101, 2017). "Consequently, the combined use of inhibitors for LAG-3/TIM-3 and PD-1 was more effective in stimulating anti-tumor immunity than blocking each individual component in different tumor mode." (PMID 27756892, 2017). "LAG-3 expression in CD4+2D2-IEL-THIGH cells from the gut was minimal, but its intracellular expression was markedly higher in the CNS-CD4+2D2-IEL-THIGH cells, similar to what was previously reported in tumour-infiltrating CD8+ T cells." (PMID 27198196, 2016). "Tumour transcriptional analysis demonstrated that, as a rapid and early consequence of vaccination, several profoundly immunosuppressive genes were highly upregulated, including CD274 (PD-L1), LGALS9 (Galectin-9), TGFβ1, LAG3 and HAVCR2 (TIM-3)." (PMID 26861383, 2016). "Similarly, blockade of the iR Lag-3 was shown to rescue tolerant CD8+ T cells in a self-tolerance and tumor model." (PMID 27314056, 2016). "To address whether alterations in checkpoint molecules in IDO-deficient mice would be recapitulated in response to combination therapy, we analyzed CD8+ lymphocytes within the tumor for immune checkpoint molecules PD-1, CTLA-4, LAG-3, and TIM-3." (PMID 27705910, 2016). "Interestingly, tumor-derived, NY-ESO-1-specific CD8+ T cells had an impaired effector function and enriched co-expression of LAG-3 and PD-1, as compared to peripheral blood CD8+ T lymphocytes." (PMID 26700461, 2016). "In addition, there were significant increases in LAG-3 and CTLA-4 expression in CD8 T cells only in Kras tumours, though the magnitude of induction was less than that observed for TIM-3." (PMID 26883990, 2016). "Dysfunctional tumor infiltrating T lymphocytes were also found to co-express PD1, LAG3 and TIM3." (PMID 27447564, 2016). "Results for this combination were promising in fibrosarcoma and colon cancer models, but tumor growth in the B16 melanoma model was not affected, possibly due to low LAG-3 and PD-1 expression on TILs in the B16 model." (PMID 27847783, 2016). "In multiple syngeneic mouse tumor models, blockade of PD-1 or its ligands promotes antitumor activity; anti-PD-1 activity in vivo can be enhanced by combination with antibodies to other T cell-negative regulators, such as CTLA-4 and LAG-3." (PMID 27234522, 2016). "LAG-3 and PD-1 are also co-expressed on CD4 and CD8 TILs in various mouse tumor models." (PMID 26347741, 2015). "MSI colorectal cancers (CRCs) comprise approximately 15 % of the total sporadic CRCs, and these tumors have been shown to upregulate expression of immune checkpoints including PD-1, PD-L1, CTLA-4, LAG-3, and IDO in tumor infiltrating lymphocytes (TILs), stroma or tumor invasive front compartments." (PMID 26174086, 2015). "Next, we determined whether checkpoint ligands for TIM-3, LAG-3 and CTLA4 were expressed on the tumor and cells within the tumor microenvironment (i.e., spleen)." (PMID 25614821, 2015). "Lymphocyte activation gene-3 (LAG-3), a CD4 homolog that binds MHC class II is yet another molecule that has been described to distinguish a unique sub-population of CD4+Foxp3+ Treg cells that expand at tumor sites." (PMID 23874336, 2013). "LAG3, a negative costimulatory molecule found on tumor-infiltrating T cells, was slightly upregulated." (PMID 23272178, 2012). "LAG-3 was found strongly expressed on Tregs present in the proximity of H/RS cells and the proportion of LAG-3-expressing lymphocytes correlated with the EBV status of the tumor." (PMID 22927872, 2012).
tumor (continued). "Within the context of tumor development and progression, overexpression of negative regulatory factors, such as PD-1 and LAG-3, has often been correlated with chronically activated and nonfunctional CD8+ T cells." (PMID 22190971, 2011). "Soluble LAG-3 (sLAG-3) binds to MHC class II molecules and induces dendritic cells (DC) to mature and migrate to secondary lymphoid organs where they can prime naïve CD4-helper and CD8-cytotoxic T cells, leading to tumour rejection." (PMID 17394654, 2007). "It provided superior tumor growth inhibition in mouse models by replenishing stem-like cells and cytotoxic effector CD8 TILs, resulting in durable responses compared to monospecific antibodies targeting PD-1 and LAG-3 separately, which eroded the stem-like T cell pool over time." (PMID 42284551, 2026). "Notably, compared with the PD‐L1− tumor group, the upregulated differentially expressed genes (DEGs) in the CD8‐C2‐Texterm subset from PD‐L1+ tumor group included exhaustion‐related genes such as HAVCR2, CXCL13, PDCD1, TIGIT, LAG3, BATF, GNLY, and CTLA4." (PMID 41194450, 2026). "Novel inhibitory and co-stimulatory immune checkpoints such as lymphocyte activation gene-3 (LAG-3), T cell immunoglobulin mucin-3 (TIM-3), T cell immunoreceptor with Ig and ITIM domains (TIGIT), OX40, CD137 (4-1BB), and CD40 are examined for their potential to enhance anti-tumor immunity." (PMID 41832248, 2026). "Among ICs, programmed cell death protein-1 (PD-1), programmed death-ligand 1 (PD-L1) and lymphocyte activation gene-3 (LAG-3) are attractive targets in immunotherapy, as they play an important role in various malignancies where they can attenuate the host immune response to tumor cells." (PMID 39929828, 2025). "Another animal study on tumor immunology found that while LAG3 blockade did not increase T cell infiltration, it doubled the proportion of tissue-localized TCRαβ + CD4-CD8-NK1.1- innate αβ T-cells (iαβTs)—these IL17-producing immune cells have been shown to possess significant anti-tumor effects." (PMID 40411616, 2025). "For example, for an immunotype with a pronounced pro-tumor profile in cancer, we can use immunotherapy, taking into account its unique features (such as the expression levels of specific molecules like CTLA-4, PD-1, Lag-3, etc. or need in monocytes reprogramming)." (PMID 40948783, 2025). "We assessed its co-expression with TIGIT, Tim-3, LAG-3, BTLA, and NKG2A across four groups: treatment-naïve CC patients and total CC patients, and peripheral CD8+ T cells from peripheral treatment-naive PBMCs versus tumor-infiltrating CD8+ T cells from biopsies of treatment-naive tumors." (PMID 41300994, 2025). "Given that LAG3 is expressed in active CD4 + and CD8 + T cells, we can view its elevation as an outward manifestation of the presence of more effector lymphocytes in the tumor tissues, whereas more lymphocytes equate to more active tumor immunity and more benefits for ESCC patients." (PMID 40411616, 2025). "The antibody’s capacity to bind PD-L1+ and LAG-3+ cells may promote the spatial organization of immune effector functions within the TME, leading to increased cytokine production and the clonal growth of tumor-specific T cells." (PMID 41239350, 2025). "While anti-tumor T cell subsets, such as T_C1_Cytotoxic cells, were enriched in the low-PCD group, the high-PCD group exhibited a significant accumulation of exhausted T cells, characterized by the expression of exhaustion markers such as LAG3, HAVCR2, CTLA4, TIGIT, and CXCL13." (PMID 40740783, 2025). "However, dual blockade of PD-L1 and LAG-3 did not result in a significant enhancement of the therapeutic response, and the number of residual tumor cells remained comparable to that observed with single-agent treatment." (PMID 40674934, 2025).
tumor (continued). "Additionally, within non-pCR tissues containing residual tumor cells, the distance between LAG3-expressing CD8 + Ki67 + T cells and tumor cells was significantly shorter than that of LAG3-negative T cells (6.77 μm vs 14.79 μm, p = 0.096)." (PMID 40411616, 2025). "Whereas the proportions of ICP-L-expressing iNKT cells (ICOSL, PDL2, and OX40L) decreased in tumors compared with non-tumoral tissues, we observed that LAG3 was the only ICP whose expression was highly heightened on tumor-infiltrating iNKT cells compared with non-tumoral tissues." (PMID 41562072, 2025). "Thus, in the context of combination treatment, arsenic sulfide inhibits THBS1 in tumor cells while upregulating CD69 and downregulating LAG3 in T cells, it is reasonable to surmise that arsenic sulfide modulates T cell activity to augment the efficacy of anti-PD-1 therapy." (PMID 41019041, 2025). "In addition to TMB, TILs, and HLA, other potential biomarkers to consider for patient stratification include LAG-3, TIM-3, and circulating tumor DNA, which may provide real-time insights into disease progression and treatment response." (PMID 40299523, 2025). "We previously generated four novel tri-specific tribodies made up of a Fab targeting 5T4, an oncofetal tumor antigen expressed on several types of tumors, a scFv targeting CD3 on T cells, and an additional scFv specific for an immune checkpoint (IC), such as PD-1, PD-L1 or LAG-3." (PMID 39929828, 2025). "Furthermore, these mono- and dual-reactive T cells differed in expression of exhaustion markers PD1+LAG3+ and CD39 suggesting that these different subsets underwent different differentiation pathways in the tumor bed possibly contributing to progenitor- and terminal-exhaustion phenotypes." (PMID 40166032, 2025). "This interesting discovery was further confirmed by the in vitro coculture of tumor cells with activated CD8+ T cells, which revealed that the reconstituted H351Q cells promoted the exhausted status of CD8+ T cells, as indicated by the increased ratio of LAG3‐ and TIGIT‐positive cells." (PMID 39830021, 2025). "Furthermore, the absence of LAG-3 enhances T-cell function, particularly when combined with the absence of PD-1, significantly improving tumor clearance." (PMID 41415289, 2025). "More recently, the addition of lymphocyte-activation gene 3 (LAG-3) inhibitors, such as relatlimab, in combination with PD-1 blockade, has demonstrated further improvement in clinical outcomes, enhancing effector T-cell activity while circumventing tumour immune escape." (PMID 40895685, 2025). "The percentage of LAG3 in each T cell subset no longer showed an obvious correlation with any spatial relationship among the tumor microenvironments, nor was there a correlation between IFN-and the average number of peritumoral T cells found in on-CCRT tissues." (PMID 40411616, 2025). "Notably, neoadjuvant regimens combining anti-PD-1 with anti-CTLA-4 or anti-LAG-3 have achieved major pathological response (MPR; defined as ≤ 10% viable tumour cells in the index lymph node) rates of 59% (n = 212, Phase 3 trial) and 63% (n = 30, Phase 2 trial)." (PMID 41291768, 2025). "Tumor models expressing the nominal antigen ovalbumin (LLCova and B16ova) had a slightly higher proportion of T cell receptors reactive to ovalbumin-immunodominant peptide SIINFEKL in B16ova compared with LLCova and similar levels of exhaustion markers such as Tim-3, PD-1, and Lag-3." (PMID 40553564, 2025). "Notably, LAG-3 positivity correlated with a higher ORR and more profound tumor shrinkage." (PMID 39751894, 2025). "Increased frequency of T cells and NK cells in the orthotopic tumor in the Tgm2 knockout mice supported an increase in immune activation, especially with an increase in both the frequency of CD4+ T cells and their elevated expression of the exhaustion markers PD-1 and LAG3." (PMID 40777010, 2025).
tumor (continued). "Given its ability to engage both T cell activation and potential ADCC via NK cells, combining cosibelimab with other ICIs, such as CTLA-4 inhibitors or newer agents targeting LAG-3 or TIGIT, could synergistically overcome resistance mechanisms and improve anti-tumor immune responses." (PMID 40299523, 2025). "ICB resistance is driven by multiple factors, including T cell exclusion and dysfunction within the TME, defects in antigen processing, a lack of tumor-associated antigens, and the presence of alternative inhibitory immune checkpoints such as VISTA, TIM-3, LAG-3, and TIGIT." (PMID 40051497, 2025). "Additionally, exhaustion markers including programmed cell death protein 1 (PD-1), T-cell immunoglobulin and mucin-domain containing-3 (TIM-3), and lymphocyte-activation gene 3 (LAG-3) were upregulated, alongside impaired tumor-killing capacity of CAR-T cells at all effector-target ratios." (PMID 40165944, 2025). "These mixed results suggest that LAG-3 may not be a universally dominant resistance mechanism across all tumor types." (PMID 40508202, 2025). "Furthermore, sncRNAs and small-molecule inhibitors targeting other immune checkpoints, such as LAG-3 and TIM-3, are under active investigation in both preclinical studies and clinical trials, offering promising potential for expanded applications in tumor immunotherapy." (PMID 41019058, 2025). "The induction of B7-H3+LAG3+ CD4+ T cells from the bone marrow of pediatric B-ALL patients and their correlation with high cytotoxic granule expression suggests a pivotal role of CD4+ T cells in controlling tumor growth in B-ALL, characterized by high HLA class II expression." (PMID 40070836, 2025). "Interactions between lymphocyte activation gene-3 (LAG-3 or CD223), T-cell immunoglobulin, and mucin domain-containing-3 (TIM-3), and their various ligands (e.g., Galectin-9, HMGB1, PS, and CD66a) diminish anti-tumor immunity through mechanisms such as inducing CD8+ T cell death and exhaustion." (PMID 38928150, 2024). "During the later phase of tumor growth (days 11–14), CD44hiCD62loTcf1–CD8+ TILs in WT mice gradually gained expression of immune checkpoint molecules (PD-1, Tim3, Lag3, Ctla4) and TOX, a master transcription factor responsible for reprograming CD8+ T cells into the exhausted state." (PMID 38787791, 2024). "Furthermore, an analysis utilizing the TSIDB database uncovered a significant correlation between AEG-1 and several key factors, including the tumor-promoting cell Th2, immune activator IL6, CXCR4, immunosuppressants CTLA4, IL1, IDO1, LAG3, PDCD1, TGFB1, and the DHC molecule HLA-DPA1." (PMID 39483471, 2024). "Interestingly, although B10 Breg cells remained unaltered in SLOs and were absent in the TME, in the present work we detected LAG-3 + B cells in all the assessed tissues and timepoints (7-, 14- and 21-days post tumor cell injection)." (PMID 38773133, 2024). "We next investigated whether these tumours had an infiltration of T cells (CD103, CD4, CD3, and CD8) and B cells (CD20) or expressed immune checkpoints (PD-L1, TIGIT, and LAG3) as these features are known to positively correlate with a response to immunotherapy." (PMID 38672534, 2024). "In addition to MHC-II, LAG-3 also binds to other ligands, such as liver sinusoidal endothelial cell lectin (LSECtin), Galectin-3 (Gal-3), and fibrinogen-like protein 1 (FGL1), which further inhibit T cell function and promote tumor immune evasion." (PMID 39743998, 2024). "Additionally, we analyzed the expression of CTLA‐4, PD‐1, LAG3, and TIGIT, which are inhibitory immune checkpoint molecules expressed in immune cells and exert inhibitory effects on the anti‐tumor functions of effector cells by binding to their respective ligands." (PMID 39659057, 2024).
tumor (continued). "At the same time, loss of NF1, TSC1, or TβRII promoted the production of soluble inflammatory mediators such as IL6 and IDO1, which resulted in a non-cell-autonomous immune-suppressive tumor microenvironment that is characterized by increased LAG3+ CD8 and CD4 T cells." (PMID 38997291, 2024). "Emerging research is also focusing on newer, less studied immune checkpoint receptors, such as lymphocyte gene 3 (LAG3) and T cell immunoglobulin and mucin protein (TIM3), which can be co-expressed on exhausted PD-1 T cells in the tumor microenvironment, promoting anti-tumor immune evasion." (PMID 39347217, 2024). "Further flow-cytometric analysis of tumor-infiltrating CD8+ T cell exhaustion and activity markers revealed that overexpression of either mHKDC1WT or mHKDC1S600A could rescue PD-1 and LAG-3 expression suppressed by mHKDC1 KD, while decreasing the expression of activity markers." (PMID 38351096, 2024). "A recent study showed that CD8 cells lacking LAG‐3 and PD‐1 mediated improved tumor clearance." (PMID 39560030, 2024). "Considering the capacity of tumor cells to promote regulatory phenotypes in the TME, and recent evidence demonstrating distinct phenotypes of Bregs, we evaluated the impact of tumor development in the expression of LAG-3 in B cells in SLOs and in the TME throughout time." (PMID 38773133, 2024). "Interestingly, a significant correlation was detected between the tumor burden and the expansion of TCRED-LAG-3KO T cells, but not with TCRED-IRCOMP T cells, suggesting a dose-dependent tumor killing in the absence of LAG-3." (PMID 38510235, 2024). "Analysis of tumor immunity revealed a characteristic immune cell signature, with a notable predominance of naïve B cells, macrophages, CD8 memory T cells, and Tregs in the SNUC microenvironment, alongside the increased expression of LAG3 in tumor‐infiltrating immune cells." (PMID 39565059, 2024). "In addition to the changes in the tumor immune microenvironment, an increased expression of PD-L1 in tumor cells, promoter methylation of CTLA4, LAG3, and PD-L1, and an abnormal expression of microRNAs can affect the efficacy of ICIs in NSCLC patients with COPD." (PMID 38291354, 2024). "Moreover, the precise anti-tumor mechanisms of LAG-3 inhibitors are not fully elucidated, which partially hinders their further development." (PMID 39743998, 2024). "However, previous attempts to reinvigorate these T cells using MRTX1257 in combination with ICIs anti–PD-1 or anti–PD-L1 and anti-LAG3 had failed to achieve any improved tumor control in our 3LL model." (PMID 39485838, 2024). "Targeting PD-1, CTLA4, LAG3, or TIM3 axis may be a potential immunotherapy-based combination strategy to enhance population of cytotoxic effector T cells in patients with high level of Rab37+/PD-1+/TIM3+ tumor-infiltrating CD8+ T cells." (PMID 38321486, 2024). "Lymphocyte activation gene-3 (LAG-3 or CD223), first discovered in 1990, is a transmembrane protein (498 amino acids) expressed primarily on the surface of activated T lymphocytes and NK cells but has also been demonstrated in APCs and certain tumor cell lines." (PMID 39346924, 2024). "The role of LAG-3 expression on circulating NK cells, as well as the expression of LAG-3 ligands on tumor cells and the early modulation of circulating cytotoxic CD4+ T cells warrant further investigation as exploitable predictive biomarkers for dual PD-1 and LAG-3 blockade." (PMID 38336861, 2024). "Analyses of Tregs in the HBV-associated HCC tumor microenvironment showed a more immunosuppressive and effective status, with increased expression levels of FOXP3, PD-1, CTLA-4, ICOS, and LAG-3 compared with non-HBV HCC." (PMID 38793588, 2024). "IL1RL1+ T cells and LAG3+ T cells may play different roles in early or locally progressive HCC, whereas in advanced stages or extensive metastases, their roles may become less significant due to changes in the tumor microenvironment." (PMID 38604154, 2024).